DNMT1 (DNA methyltransferase 1)
Diseases named in the same sentence as DNMT1 in open-access papers (continued):
Sharing a sentence is not in itself a finding about the gene and the disease.
tumor (continued). "Since the pretreatment tumor biopsy material was not available in the current trial, the measurement of DNMT1 expression was performed with peripheral blood mononuclear cells (PBMCs) by western blot analysis." (PMID 25895027, 2015). "Hence, we investigated the effects of the high fat diets on DNMT function, determining mRNA levels of DNMT1, DNMT3a and DNMT3b, as well as DNMT activity in mammary gland and tumor at 246 days of age." (PMID 26401660, 2015). "MiR-148a was found to bring about tumor-suppressive effect by targeting NRP1, ROCK1 and DNMT1." (PMID 26097868, 2015). "Differential hypomethylation of known regulatory elements such as the DNA replication initiation site located in the first intron of DNMT1 gene (A-8 HMR) and the estrogen receptor binding sites within intron 2 of SLC22A5 (B-5 HMR) were also observed in tumor cells." (PMID 25706888, 2015). "They found that tumor burden, but not tumor size, is significantly reduced with decreasing DNMT1 levels, suggesting that DNA methylation is involved in pancreatic tumorigenesis in this mouse model." (PMID 24822169, 2014). "In contrast, DNMT3a was decreased in the castrated mice (P < 0.05), and DNMT1 and DNMT3b were both significantly decreased in the combination group (P < 0.01 and P < 0.05, respectively), which was not consistent with the tumor sizes in the different groups." (PMID 24885368, 2014). "In a statistical study with TNM staging and history of chronic pancreatitis, DNMT3A and DNMT3B, but not DNMT1 expression, correlated with tumor size." (PMID 24822169, 2014). "And HBx expression could up-regulate DNMT1, DNMT3A1, and DNMT3A2 activities and selectively promoted hypermethylation of specific tumor suppressor genes." (PMID 23347460, 2013). "HCT116 WT and HCT116 DNMT1/3B DNA were used as positive and negative controls, respectively, to determine DNA methylation in each tumor sample." (PMID 23505554, 2013). "The results of the present study demonstrated that DNMT1, 3a and 3b proteins were highly expressed in PDAC tissues, suggesting that DNMTs may be targets for carcinogenic environmental factors to affect tumor suppressor gene methylation." (PMID 24423239, 2013). "To investigate DNMT1 implication in the generation of chromosomal instability (aneuploidy), we evaluated the effects of its depletion by RNA interference in primary human fibroblasts (IMR90) and in near diploid human tumor cells (HCT116)." (PMID 22305267, 2012). "The expression of DNMT1 was not correlated with age (P = 0.060), tumor size (P = 0.131), clinical stage (P = 0.113), differentiation (P = 0.902) or lymph node metastasis (P = 0.972)." (PMID 22455563, 2012). "In others terms, these results suggest that the DNA is less methylated in tumor cells than in non-tumor cells since tumors cells harbored less Dnmt1/PCNA interactions." (PMID 21470401, 2011). "We found that the high level of DNMT1 expression was significantly associated with poor overall survival in NSCLC patients, independent of tumour stage and grade." (PMID 18414412, 2008). "The concurrent inhibition of EZH2 and DNMT1, but not individual agents, significantly boosts T cell infiltration, slows down tumor progression, and enhances the therapeutic response to the PD-L1 checkpoint blockade in tumor-bearing mice." (PMID 39858465, 2025). "Moreover, DNMT1 knockdown increases miR-484 expression via demethylation of its promoter, decreasing cell migration, invasion, EMT, cell adhesion, and tumor growth via downregulation of β-integrin, WNT/MAPK, and TNF-α signaling pathways in HeLa and C-33A CC cells." (PMID 41226543, 2025). "Concordantly, DNMT1 is overexpressed in tumor cells compared to non-tumoral cell lines." (PMID 39273054, 2024). "However, Dnmt1 re-expression in Sox9 CKO livers slightly but significantly restored tumor formation driven by Akt-NRAS, but not Akt-YAP1, implying the partial involvement of Dnmt1 in Akt-NRAS tumor development under the SOX9." (PMID 39273023, 2024).
tumor (continued). "However, the sh-DNMT1 group did not exhibit superior tumor suppression compared to the other two groups treated with inhibitors." (PMID 38755637, 2024). "We first assessed whether G9a and DNMT1 expression was different in tumor specimens from NSCLC patients and in non-malignant lung samples." (PMID 39488528, 2024). "Therefore, it is reasonable to infer that the DNMT1/miR-152-3p negative feedback loop critically sustains self-renewal and tumor growth of LCSLC through SOS1." (PMID 38622665, 2024). "Additionally, DNMT1 pharmacological inhibition alone and in combination with SMO inhibition effectively inhibits tumor growth in murine and human SHH-MB cell models and prolongs survival of SHH-MB mouse models by inhibiting SHH signaling output downstream of SMO." (PMID 39107797, 2024). "An increased expression level of DNMT1 has been found in tissue samples from metastatic breast tumors, whereas upregulation of DNMT3A and DNMT3B has been observed mainly at an early stage of tumorigenesis, implying a tumor stage-dependent expression pattern of these enzymes." (PMID 39334883, 2024). "Inhibition of DNMT1 by DNMT inhibitors as a class of drugs that target the epigenetic regulators and other approaches, such as antisense oligonucleotide, reduces the DNA methylation level and reactivates expression of tumor suppressors such as p16ink4A and/or p15ink4B." (PMID 39057134, 2024). "Further studies will be required to understand the role of DNMT1 in regulating the EBV latency program and potential combination therapies that may enhance latency switching and/or enhance the immune response to a latency-converted tumor." (PMID 38464537, 2024). "Interestingly, similar to DNMT1 inhibition, ablating the histone demethylase LSD1, which is elevated in diverse cancers, improves tumor immunogenicity by simultaneously activating the dsRNA-IFN pathway by stimulating ERV expression and downregulating the RNA-induced silencing complex (RISC)." (PMID 36600243, 2023). "Other authors reported that the deletion of DNMT1 in mice decreased the number of Treg cells in lymphoid organs and that patients on trial with guadecitabine and anti-PD1 (pembrolizumab) showed a reduced number of Treg cells compared to baseline in tumor biopsies." (PMID 36934257, 2023). "The fact that depleting UHRF1 or DNMT1 enhances differentiation of THP-1 cells and inhibiting tumor growth in xenograft mice strongly suggest that targeting UHRF1 or DNMT1 might be a novel therapeutic strategy to treat MLL-AF9 AML by inhibiting cellular proliferation and inducing differentiation." (PMID 37573395, 2023). "However, our data show that subcutaneous injection of MCF10A cells exposed to FolateRDI/Diuron3MAC/PFOA3MAC does not induce tumor formation as does the injection of MCF10A cells that have lost the integrity of the DNMT1/PCNA/UHRF1 complex." (PMID 36278678, 2022). "Considering the high expression of DNMT3A, TET1, DNMT3B, TET3, UHRF2, DNMT1, UHRF1and TDG in Subtype B, changing the tumor microenvironment cell infiltration characteristics by reversing expression of these DNA methylation regulators may be more clinically practical." (PMID 35771147, 2022). "Notably, abrogation of DNMT1 did not interfere with ALK levels or activity in ALKKO transgenic mice as indicated by similar pALK levels in ALK tumor cells and ALKKO thymocytes nor did it change pSTAT3 levels." (PMID 33310759, 2021). "Notably, the tumor growth of xenografts from DNMT1 knockdown 786‐O cells was not suppressed by treatment with temsirolimus, while that of 786‐O xenografts was significantly inhibited by temsirolimus." (PMID 33107222, 2021). "In our KURC3 PDX tumors, the DNMT1 mutation was not identified initially, and it is suggested that this mutation would not be related to carcinogenesis or early progression of the KURC3 tumor." (PMID 33107222, 2021).
tumor (continued). "Therefore, it was speculated that m5C methylation modification mediated by DNMT1 may contribute to activated DCs in the TME, thus promoting the anti-tumour immune response in HCC." (PMID 34589490, 2021). "Early studies show the canonical function of UHRF1 as a multifunctional protein is in the recruitment of DNA methyltransferase 1 (DNMT1) to DNA loci, thereby facilitating DNA hypermethylation, which plays important roles in cell proliferation, cell cycle progression, and tumor aggressiveness." (PMID 34465029, 2021). "Besides, both univariate and multivariate Cox analyses revealed that the risk score could act as an independent prognostic factor in HNSCC, implying that NSUN5, DNMT1, and DNMT3A could be involved in tumor oncogenes and suppressors." (PMID 33912441, 2021). "Therefore, we speculated that DNMT1 changed the methylation status of TAP1 and affected the infiltration of tumor immune cells thereby changing the prognosis of OC, which was worthy of further verification." (PMID 34957213, 2021). "On the other hand, the tumor suppressor role of miR-342-3p via inhibition of cell proliferation, migration and invasion has been demonstrated in colon, lung, breast and hepatocellular carcinoma, by downregulation of oncogenic targets, including FOXQ1, DNMT1, MYC and IKK-γ." (PMID 33076962, 2020). "Moreover, elevated DNMT1 could reverse the effect of miR‐152‐3p upregulation on CRC development and tumor growth." (PMID 32918845, 2020). "However, DNMT1 expression was not related to tumor location, Laruen's classification, depth of invasion, lymph node metastasis or vascular metastasis of GC (p > 0.05)." (PMID 29221215, 2017). "Thus we can conclude that 3,6-DHF inhibits DNMT1 activity, modulates the imbalance of DNA methylation and demethylation status, increases TET1 expression, re-expresses miR-34a, and as a consequence, prevents breast carcinogenesis." (PMID 28870206, 2017). "We found higher DNMT1 mRNA levels compared to de novo DNMT in both tissues and in all experimental groups, according to the literature, and a coordinated expression of DNMT1, DNMT3a and DNMT3b in mammary gland and tumor, as it has been described in several tissues." (PMID 26401660, 2015). "Overexpression of DNA methyltransferase 1 is not a secondary result of increased cell proliferative activity, but is significantly correlated with accumulated DNA hypermethylation in the CpG islands of tumor-related genes." (PMID 25815725, 2015). "As a type of DNMT1 inhibitor, DAC has been shown to reactivate tumor suppressor genes that have been silenced by promoter DNA methylation, in order to restore their function of inducing apoptosis, inhibiting tumor cell growth and providing therapeutics for chemotherapy-resistance tumors." (PMID 23946818, 2013). "Expression of DNMT1 appeared to be a protective factor in patients whose tumor occurred in both sides but it is not statistically significant (OS, P = 0.139) (DFS, P = 0.269); opposite of findings from patients whose tumor occurred in single side (OS, P = 0.429) (DFS, P = 0.210)." (PMID 22768205, 2012). "RG108 is a small molecule that specifically fits into the active site of human DNMT1 and renders the enzyme inactive, inducing demethylation and reactivation of tumor suppressor genes, without affecting the methylation status of the centromeric satellite sequences." (PMID 21629434, 2010). "However, miR-148a expression was inversely correlated with the expression of DNMT1 (ρ = − 0.31, P = 0.04), whereas miR-148b expression showed negative correlation with the expression of DNMT3A (ρ = − 0.38, P = 0.02) and DNMT3B (ρ = − 0.33, P = 0.03) in tumor tissues from 42 NSCLC patients." (PMID 36959680, 2023).
tumor (continued). "Considering our comprehensive analysis of DNMT expressions across the progression of OEC, we hypothesize that DNMT1 and DNTM3A seem to play a role in tumor initiation, DNMT3B in tumor progression and DNMT3L in tumor relapse, whereas DNMT2 may have an opposite role, acting as a tumor-suppressor gene." (PMID 37894317, 2023). "The trapping of PARP1 and DNMT1 to chromatin, acetylation of DNA repair proteins, and down-regulation of NuRD may all have increased double-strand DNA break (DSB) formation as suggested by activation of the DNA-damage response, concomitantly resulting in tumor cell death." (PMID 29423093, 2018). "However, since correlation analysis between DNMT1 and CpG methylation in high-grade tumors does not distinguish between tumor subclasses, it is possible that tumors from the classical or neural subtype might also consistently show high or low levels of DNMT1." (PMID 28036297, 2017). "However, we did not observe DNMT1 downregulation after treating normal peripheral blood mononuclear cells (PBMCs) with curcumin, thus suggesting that curcumin may selectively downregulate DNMT1 expression in tumor cells, but not in normal cells." (PMID 23457487, 2013). "To validate the possibility to use the Dnmt1/PCNA P-LISA to evaluate the degree of DNA hypomethylation in cells, we compared whether the number of Dnmt1/PCNA interactions was correlated with the values of 5 mC number quantification (ELISA method) in non-tumor and tumor breast cell lines." (PMID 21470401, 2011). "The results showed that F. nucleatum and its culture supernatant did not increase the activity of DNMT1 and DNMT3B in COLO 205 cells or the activity of DNMT1, DNMT3A, and DNMT3B in subcutaneous tumor tissue of nude mice infected with F. nucleatum." (PMID 40458404, 2025). "We aimed to demonstrate that the DNMT1/miR-152-3p negative pathway upregulates SOS1 expression in NSCLCs to induce self-renewal and tumor growth in CSLCs." (PMID 38622665, 2024). "Consistent with cultured cells, was the marked increase of DNMT3B expression—but not DNMT1 and DNMT3A—in GLO1-depleted MDA-MB-231 tumor xenografts when compared with control tumors." (PMID 36998085, 2023). "Advanced-grade tumors had higher DNMT1 gene expression level compared with lower grade tumor samples, but TNM stages and lymphatic invasion did not correlate with DNMT1 expression." (PMID 33500531, 2021). "Our results suggest that in the absence of DNA damage, DNMT1, and JAK/STAT signaling, IL-6 release most likely plays a role in differentiation, as observed by reduced CK-5 expression, and elicits anti-tumor activity in MIBC cells." (PMID 29242529, 2017). "In accordance with previously published data, also DNMT1 mRNA levels were significantly higher in ARMS and ERMS tumours compared to NSM (30.5±9.0, data not shown)." (PMID 27764816, 2016). "Another study confirmed a significant down-regulation of miR-148a in HCC, indicating that this miR exerted its tumor-suppressive effect by regulating the c-Met oncogene, regardless of the DNMT1, the DNA methyltransferase 1, expression level." (PMID 28536397, 2015). "Tumors in the group transplanted with DNMT-shRNA-transfected U251/TM cells were larger than the tumors in the negative control+TMZ group on days 13–21, whereas the tumor growth induced by knockdown of DNMT1 was suppressed by miR-20a inhibitor treatment." (PMID 26337869, 2015). "However, overexpression of methylating enzymes (DNMT1 and DNMT3B) enzymes was not a critical determinate of tumor-specific promoter hypermethylation of RASSF1A and FUS1, which revealed, respectively, high and moderate methylation frequency in our study." (PMID 26112163, 2015). "This suggests that variable methylation patterns could be a by-product of tumor dedifferentiation and possibly DNMT-1 (DNA methyltransferase 1) overexpression without regulatory links to mRNA-expression." (PMID 23718921, 2013).
tumor (continued). "Although the expression of p18INK4C was partially affected by DNMT1, no significant upregulation of DNMT1 (P > 0.05) or DNMT3B (P > 0.05) mRNA levels was observed in 35 GC tissues (the same tissues used to detect DNMT3A expression) compared with non-tumor tissues." (PMID 26350239, 2015). "In conclusion, these results suggested that although changes in DNMT1 activity may contribute to alterations of THRB expression in cell cultures, the disturbed expression of THRB in ccRCC tissue samples is rather not a result of aberrant, tumor-specific hypermethylation of the gene’s promoter." (PMID 24849932, 2014).